KCNN3 (potassium calcium-activated channel subfamily N member 3)
Diseases named in the same sentence as KCNN3 in open-access papers (continued):
Sharing a sentence is not in itself a finding about the gene and the disease.
Zimmermann-Laband syndrome (3 papers, 2023 to 2025). A rare disorder characterized by gingival fibromatosis, coarse facial appearance, and absence or hypoplasia of nails or terminal phalanges of hands and feet. "Clinical features of subjects with biallelic TBC1D2B pathogenic variants show phenotypic overlap with syndromic neurodevelopmental K+ channelopathies or Zimmermann-Laband syndrome associated with dominant KCNN3, KCNH1, and KCNK4 variants." (PMID 38374468, 2024).
cognitive deficits (2 papers, 2024 to 2025). "Overexpression of KCNN3, a candidate gene linked to SCZ that encodes the small‐conductance calcium‐activated K (+) channel 3 (SK3), in the forebrain is thought to cause core cognitive deficits associated with SCZ." (PMID 39924342, 2025).
familial hemiplegic migraine type 2 (2 papers, 2011 to 2025). "Genes coding for small conductance calcium-gated potassium channels (SKCa) such as KCNN3 have been associated with Familial Hemiplegic Migraine in some pedigrees, alongside the more well known CANCA1A and ATP1A2." (PMID 40823308, 2025). "The calcium-activated potassium ion channel gene (KCNN3) is located in the vicinity of the familial hemiplegic migraine type 2 locus on chromosome 1q21.3." (PMID 22030984, 2011).
Anxiety (1 paper, 2020). Intense feelings of nervousness, tension, or panic often arise in response to interpersonal stresses. "Amygdalar expression of Kcnn3 correlated significantly with 40 anxiety-associated phenotypes." (PMID 33247097, 2020). "Using an exploratory analysis targeting BLA K+ channel genes of BXD RI strains, we identified a Kcnn3 eigentrait for anxiety- and activity-related behavioral traits." (PMID 33247097, 2020). "Thus the results from our exploratory bioinformatics analysis add to a growing literature implicating Kcnn3 in anxiety-related and alcohol drinking behaviors and identified a top target that was further explored in a chronic alcohol and stress exposure model." (PMID 33247097, 2020). "In addition to the genetic evidence for Kcnn3 and anxiety-related behaviors, BLA Kcnn3 expression was also negatively correlated with alcohol drinking traits in BXD RI strains." (PMID 33247097, 2020). "Further examination of Kcnn3 expression in the amygdala (but not nucleus accumbens—data not shown) revealed a strong eigentrait for anxiety-like and activity-based behaviors." (PMID 33247097, 2020). "Further examination of Kcnn3 expression revealed a strong eigentrait for anxiety-like behaviors and negative correlations with binge-like and voluntary alcohol drinking." (PMID 33247097, 2020).
colorectal cancer (1 paper, 2019). A primary or metastatic malignant neoplasm that affects the colon or rectum. "In breast and colorectal cancers (BC and CRC), σ1R is required to trigger the physical and functional coupling between the Ca2+ channel Orai1 and the Ca2+-dependent K+ channel SK3 (KCNN3)." (PMID 31780884, 2019).
deafness (1 paper, 2025). An inherited or acquired condition characterized by the complete loss of the ability to hear from one or both ears. "In human patients, KCNN3 and NTN1 have both been implicated in conditions related to hair growth, including onychodystrophy syndromes and deafness." (PMID 40725390, 2025).
encephalitis (1 paper, 2025). An acute inflammatory process affecting the brain parenchyma. "The resultsindicated that in the encephalitis group, potassium channel-related gene KCNN3,cell development-related genes EMC8, DANCR, and ASPN, along with thetranscription factor ZNF296, were significantly upregulated." (PMID 40985687, 2025).
fibrosis (1 paper, 2021). the formation of excess fibrous connective tissue in an organ or tissue in a reparative or reactive process. "Various genes which are potentially regulated by this miRNA are involved in calcium and potassium handling in myocytes (CACNB2, KCNN3), in protection of cells against oxidative stress (SIRT1), and in regulating cardiac fibrosis (STAT3)." (PMID 35052352, 2021).
glioblastoma (1 paper, 2025). The most malignant astrocytic tumor (WHO grade IV). "Glioblastoma studies included E5 (KCNJ10, KCNN3), E21 (KCNAB2), E26 (KCNE2, KCNJ13), E27 (KCNE4, KCNMB2-AS1), E31 (KCNJ10), E50 (KCND3), and E51 (KCNIP1, KCNJ16, KCNN2)." (PMID 40867621, 2025).
Hypotonia (1 paper, 2021). Hypotonia is an abnormally low muscle tone (the amount of tension or resistance to movement in a muscle). "Hypotonia was present in 26/27 (96%) individuals with dominant KCNH1 variant, in 4/6 (67%) with dominant KCNN3 variant, and in 2/3 (66%) with dominant KCNK4 variant." (PMID 33594261, 2021).
Left atrial enlargement (1 paper, 2017). Increase in size of the left atrium. "Therefore, we hypothesized that PITX2, KCNN3 and ZFHX3 associate with left atrial enlargement and persistent AF and subsequently with ablation outcome." (PMID 28381281, 2017).
oligodendroglioma (1 paper, 2021). A well-differentiated (WHO grade II), diffusely infiltrating neuroglial tumor, typically located in the cerebral hemispheres. "Finally, we observed a higher level of APOE, BMP4, KCNN3/SK3, and CRYAB proteins in astrocyte-like cells, whereas the IDH1 enzyme appears to be more expressed in oligodendrocyte-like cells in oligodendroglioma." (PMID 33925547, 2021).
Tinnitus (1 paper, 2020). Tinnitus is an auditory perception that can be described as the experience of sound, in the ear or in the head, in the absence of external acoustic stimulation. "Data from the present study provides the first association of KCNN3 gene with the symptom of tinnitus in human samples." (PMID 33192958, 2020). "Notably, we identified KCNN3, SOD3, MUC4, GALR1, and WDR45B, which are implicated in auditory function, as differentially methylated associated with self-reported tinnitus." (PMID 33192958, 2020). "Notably, tinnitus symptom analyses identified regions with differential methylation in genes KCNN3, MUC4, GALR1, SOD3, and WDR45B (in the low vs. high cumulative blast exposed groups." (PMID 33192958, 2020).
cancer (21 papers, 2012 to 2024). A tumor composed of atypical neoplastic, often pleomorphic cells that invade other tissues. "This was associated with a large reduction of the expression of the SK3 protein and KCNN3 mRNA in various cancer cell lines." (PMID 38642894, 2024). "Thus, mRNA levels of KCNN2 and KCNN3 channels may constitute a promising prognostic marker or interesting targets to regulate chemosensitivity of several cancers." (PMID 38480668, 2024). "Additionally, the gene targets of these miRNAs included several cancer driver genes including ZNF704 (targeted by ten miRNAs), MMP16 (targeted by eight miRNAs), and KCNN3, POU2F1, ADARB1, MPZL1, RUNX1T1, UBE2W, and DYRK1A genes (targeted by seven miRNAs)." (PMID 37685851, 2023).
tumor (13 papers, 2012 to 2026). "These latter findings were correlated with shorter disease-free survival in samples with lower KCNN3 expression, suggesting that KCNN3 could be a tumor suppressor, therapeutic target, and a marker of poor prognosis in OC." (PMID 37375748, 2023). "The first cluster exhibits upregulation of CXCL12, PTGDS, KCNN3, suggesting CXCL12-high fibroblasts in the immune infiltrated stroma within the tumor microenvironment (TME)." (PMID 41249066, 2025).
neurodevelopmental disorder (3 papers, 2022 to 2025). A behavioral and cognitive disorder with onset during the developmental period that involves impaired or aberrant development of intellectual, motor, or social functions. "It is a syndromic neurodevelopmental disorder that shared notable phenotypic overlaps with the syndrome caused by variants of potassium channel-encoding genes KCNN3 and KCNH1." (PMID 36683851, 2022). "It is important to note, however, that mutations in KCNN3 that have been related with Zimmermann-Laband are a gain-of-function mutation or mutations that involve a loss of function of the channel have been linked with neurodevelopmental disorders." (PMID 41164793, 2025). "With increasing variants identified, the phenotypic spectrums of KCNN3 and KCNH1 are expanding, from syndromic neurodevelopmental disorder to pure epilepsy." (PMID 36683851, 2022).
brain disease (2 papers, 2017 to 2025). "In further review of the literature, no documented studies were found that focused solely on the possible link of the structural variants of KCNN3 with brain diseases." (PMID 41164793, 2025). "KCNN3 genomic variants have been associated with brain disease and SK channels are expressed widely in brain and play a key role in the control of neuronal activity; thus, drugs modulating SK3 activity may be useful to treat neuropsychiatric disorders." (PMID 41164793, 2025).
psychiatric disorder (2 papers, 2016 to 2023). A disorder characterized by behavioral and/or psychological abnormalities, often accompanied by physical symptoms. "It is noted that 7 genes, DAO, PRDX6, KCNN3, TCF7L2, RFX4, FYN, and B3GAT2 (yellow-colored nodes), relevant to psychiatric disorders are involved and interestingly these genes except B3GAT2 constitute a connected subgraph." (PMID 27510319, 2016).
KCNN3 also shares sentences with these, for which no sentence is quoted: colon cancer (11 papers); endothelial dysfunction (8); diabetes (6); melanoma (5); type 2 diabetes mellitus (5); bipolar disorder (4); cardiovascular diseases (3); colitis (3); Obesity (3); pancreatic cancer (3); alcohol use disorder (2); Arrhythmia (2); atherosclerosis (2); catecholaminergic polymorphic ventricular tachycardia (2); erectile dysfunction (2); glioma (2); mood disorder (2); preeclampsia (2); pulmonary hypertension (2); adenocarcinoma (1); and epileptic encephalopathy (1); Anorexia (1); anorexia nervosa (1); anxiety disorder (1); autosomal dominant cerebellar ataxia (1); bladder cancer (1); cardiac disease (1); cardiomyopathy (1); central nervous system disorder (1); channelopathies (1).
A further 42 diseases each share a sentence with KCNN3 in 1 paper.